CD4 (CD4 molecule)
Diseases named in the same sentence as CD4 in open-access papers (continued):
Sharing a sentence is not in itself a finding about the gene and the disease.
infection (continued). "Upon secondary infection, the relative and absolute numbers of IFN-γ-producing Lm OVA-specific CD8+ T cells strongly increased in A20fl/fl mice, whereas absolute numbers only slightly expanded in CD4-Cre A20fl/fl mice." (PMID 28004776, 2016). "Our data shows the frequency of CD4+ RTEs expressing the activation marker CD44 increases significantly in L. donovani-infected animals, suggesting that CD4+ RTEs are at least partially activated during an ongoing infection." (PMID 27658046, 2016). "To clarify if Vpr is capable of enhancing productive infection of non-activated primary CD4+ T cells, we used NL4-3-based infectious HIV-1 expressing non-signalling murine heat-stable antigen (HSA) at the surface as a marker of infected cells upon replication." (PMID 27383627, 2016). "Whether endogenous antigen-specific aged CD4+ T cells have the ability to acquire a TFH cell phenotype and/or whether endogenous aged TFH cells have functional defects during infection remains unclear." (PMID 27109638, 2016). "The number of FOXP3 expressing lung CD3+CD4+ T cells was increased at 7 days post-infection in both w/t and Tbet-/- mice, but was not different between the 2 mouse strains." (PMID 27683080, 2016). "From these data, we conclude that virion packaged Vpr and its presence in the cell directly post-entry is sufficient to confer productive infection of non-activated CD4+ T cells." (PMID 27383627, 2016). "Based on extensive data on the effect of enteric E. coli (gram-negative) on LP CD4 T cell infection, activation and depletion, E. coli was included as a positive control." (PMID 26762145, 2016). "In a previous study of morphometry over time we found that HIV had little effect on mucosal architecture over and above EE, except for an increase in crypt depth at all stages of infection and an increase in lactulose permeation only in late stage HIV (CD4 cells < 200 cells/μl)." (PMID 27050312, 2016). "Comparable turnover of CD4+ T-cell subsets irrespective of SIV-infection status likely contributes to the lack of aberrant immune activation and disease progression observed after infection in non-progressive hosts." (PMID 27227993, 2016). "We found that Mtb-specific frequencies of effector T cell phenotypes (i.e., both CD4+ and CD8+) in the blood can be targeted to distinguish infection outcomes, with a clear separation between median trajectories of active versus latent TB late during infection progression (~300 days)." (PMID 27065304, 2016). "The frequency of cells expressing perforin or granzyme B was significantly greater in CD38+ CD4+ T cells than in CD38- CD4+ T cells prior to and post infection (p = 0.001 and p = 0.011 prior to infection, and p = 0.012 and p = 0.017 at peak infection for perforin and granzyme B, respectively)." (PMID 27662621, 2016). "We found not only that IL-27 instructs IL-10 expression by CD4+ IFN-γ+ T cells within the spleen during malaria infection, as previously shown, but also that it controls IL-10 production by CD4+ T cells in nonlymphoid tissues during infection." (PMID 26459508, 2016). "Prior to day 6 post-infection, for example, Icos−/− CD4+ T cells were not defective in their ability to express the canonical Tfh cell markers Bcl6, PD-1, CXCR5, or IL-21." (PMID 27559335, 2016). "The % of CD4+IFN-γ+ cells was very low after a primary infection and not significantly different from controls." (PMID 27905502, 2016). "Mechanistically, these variable outcomes of CCR5 deficiency in infectious diseases have been largely attributed to its regulatory effect on trafficking of leukocytes, including NK, CD4, CD8, and CD4+Foxp3+ Treg cells to the site of infection as a consequence of the elevated immunopathology." (PMID 27439902, 2016). "Further, in the LCMV model of infection, blockade of type-I IFN receptor signaling in certain situations may enhance CD4+ T cell immunity and control of virus chronicity, an outcome associated with reduced development of immune-suppressive DCs." (PMID 27926930, 2016).
infection (continued). "BmA, but not ES-62, had the capacity to bind the C-type lectin dendritic cell-specific intercellular adhesion molecule-3-grabbing non-integrin (DC-SIGN) thereby inhibiting HIV-1 trans-infection of CD4+ enriched T-cells." (PMID 26808476, 2016). "Primary CD4+ T cells were then co-cultured with HIV-1 with the presence or absence of AAT/C/ΔAAT to detect cis-infection of HIV-1." (PMID 27473095, 2016). "In the present study, we addressed this question by utilizing HLA class II tetramer reagents to directly characterize WNV specific CD4+ T cell responses in subjects with previous WNV infection and compared the immune phenotype in subjects with asymptomatic infections versus neuroinvasive disease." (PMID 26795118, 2016). "Given the long life span of resting CD4 T cells and the stability of circularized HIV-1 uDNA in them, we investigated the kinetics of gene expression from uDNA vs. iDNA in these cells after a single round of infection." (PMID 26728316, 2016). "Using our techniques, it will now be possible to quantify the number of latently infected CD4+ T cells and persistently infected myeloid cells that harbor replication-competent virus in SIV-infected macaques in which infection is suppressed by ART to advance our understanding of HIV latency." (PMID 27030272, 2016). "We assessed the ability of the panel of SHIVs to replicate in immortalized pig-tailed macaque (Ptm) CD4+ lymphocytes in the presence and absence of IFNα-2a at a concentration similar to that observed in natural infection (1000 U/ml)." (PMID 27399306, 2016). "However, as with splenocytes, the increasing cellularity of the MRLN was masking significant changes in absolute numbers of cells, since the total numbers CD4+ and CD8+ T cells, B cells, and granulocytes all increased in lymph nodes following infection." (PMID 27315117, 2016). "An inverse trend of TGF-β vs. PD-1 expression was observed with infection, which was altered to a positive correlation upon METH exposure in CD4 and CD8 T cells (CD4—LCMV vs. LCMV-METH–r = -0.0965 vs. r = 0.1949; CD8—LCMV vs. LCMV-METH–r = -0.06738 vs. 0.3093)." (PMID 27760221, 2016). "Furthermore, most of the immune-related genes, particularly TLR7, TRAF3, Mx, TRIM25, CD4, and CD8α, increased in response to GPV and H9N2 infection." (PMID 27916934, 2016). "Also, we have estimated rate constants for how IFNα interacts with CD4 T cells and HIV-1, thereby providing a realistic range in which to perform simulations of infection." (PMID 27010978, 2016). "In the CD4-depleted, mRNA vaccinated group, all mice had to be sacrificed within 11 days after infection with similar kinetics as in the negative control group in line with the strongly reduced VN titers in this group." (PMID 27336830, 2016). "Examination of the distribution of antigen-specific CD4 T cells between Tfh and NonTfh populations after infection revealed the potential relationship between specificity and function, with some epitope-specific populations favoring Tfh function over NonTfh." (PMID 27329272, 2016). "Average CD4+ cell count (/μl) of HIV-infected mothers over pregnancy did not affect infection status of their newborns." (PMID 27721453, 2016). "In BALF, CD4+ T cell and B cell (CD79+) percentages and total number of cells were similar in mock-infected animals and infected animals on day 2 and day 5 post-infection." (PMID 27315117, 2016). "The survival rate of CD4+ T cell recipients, however, was lower than that of CD8+ T cell recipients, indicating that CD4+ T cells are less efficient in protecting animals with already advanced infection." (PMID 27875529, 2016). "Together, these data revealed that direct infection of resting CD4+ T-cells, in the absence of additional stimuli, is possible in some donors at higher viral titres." (PMID 27383184, 2016). "The CD4+ YFP+ GFP+ T cells exhibited a largely equivalent profile on day 14 of infection (results not shown)." (PMID 26459508, 2016).
infection (continued). "Because our ICS assays showed Chlamydia-specific CD4+ T cell effector function was primarily characterized by IFN-γ production, we posited TH1-type immunity conferred protection against ivag C. trachomatis challenge infection." (PMID 27606424, 2016). "IL-21 transcript levels were induced 10-fold in CD4+ T cells following infection; in contrast, little or no transcript was detected in CD8+ T cells." (PMID 27819295, 2016). "CD4 T cells expressing GrB and perforin can be found at the site of infection, the lung, but not the DLN or spleen, after IAV infection." (PMID 27014272, 2016). "Thus, it remains a priority to improve the understanding of the role of CD4+ and CD8+ T cell responses in natural infection as well as in vaccine approaches." (PMID 27900319, 2016). "For example, IFNγ levels in the skin increased in rainbow trout upon infection with Gyrodactylus salaris although in this case other T related genes such as CD4 or CD8 were not significantly modulated by the infection." (PMID 26808410, 2016). "Noticeably, the CD4 mRNA was increased in the HEP-Flury infected mouse brains but was down-regulated in the brains of CVS-11 infected mice, and CD8 mRNA was up-regulated more significantly in response to the infection with HEP-Flury." (PMID 27242764, 2016). "As transfer of PD1-/- CD4+ T cells replicates the phenotype of intact PD1-/- mice, and leads to increased bacterial burden and lung necrosis, it is likely that that PD1 has an important immunoregulatory role early during infection." (PMID 26967901, 2016). "In the context of Mycobacterium tuberculosis infection, for example, mice lacking expression of ICOS exhibited evidence of enhanced Th1 immunity, producing a significantly greater number of CD4+IFN-γ+ T cells in the spleen and lungs during later stages of infection." (PMID 27559335, 2016). "The extent of infection of monocytes and macrophages has not been rigorously assessed with assays comparable to those used to study infection of CD4+ T cells and to evaluate the number of CD4+ T cells that harbor infectious viral genomes." (PMID 27030272, 2016). "Surprisingly, the bacteria were not present anymore in the five CD4+ recipients that succumbed to the infection." (PMID 27875529, 2016). "On day 3 post-infection, IFNγR2 was expressed on a low percentage of CD4+ T cells and the percentage of IFNγR2+ CD4+ T cells was not significantly different in the FeD mice compared to the control mice." (PMID 25768944, 2015). "However, by 7 and 10 days post infection both the percentage and the absolute number of IFN-producing CD4+ T cells were significantly enhanced in IL-27R-/- mice when compared to wild-type cohorts." (PMID 26222157, 2015). "In survival experiments, CD8-/-JHT mice either in the presence or absence of CD4+ T cells exhibited long-term control of the infection further indicating efficient virus control in the absence of CD8+/CD4+ T cells as well as B cells." (PMID 25658831, 2015). "This post-infection increase in parasite specific antibody is not influenced by parasite density of the booster infection episode or blood CD4 +cell counts (at least > 350 CD4 /uL) of the convalescent patient." (PMID 25906165, 2015). "Importantly, these three PKC agonists exhibit anti-viral activity by downregulating the expression of the HIV-1 receptor CD4 and the coreceptors CXCR4 and CCR5 on the host cell surface, which would lead to the blockade of de novo infection." (PMID 26225566, 2015). "To explore the significance of IL-21-mediated viral inhibition, we assessed CD4 T-cell depletion in HLACs in the presence and absence of IL-21 6 days post infection." (PMID 26108174, 2015). "Vpx allows the non-productive infection of resting CD4+ T cells, but does not confer HIV-2 with the ability to efficiently infect MDDCs." (PMID 25582927, 2015). "Without infection, WT and KO cells reconstituted the CD4 and CD8 population equally well at 8 weeks post-adoptive transfer (time point 0)." (PMID 26565411, 2015).
infection (continued). "The analysis of the T cells in the blood of the IP infected animals, 11 days after infection, showed no change in the number of CD4+ and CD8+ cells when compared to control group." (PMID 26469517, 2015). "Cytokine production analysis by flow cytometry revealed, at week 2 post-infection, higher amounts of IFN-γ in lungs of mice receiving CD4+Foxp3- T cells in comparison to the other groups, which is consistent with the elevated levels of Tbet expression found in the lungs of mice from this group." (PMID 26512987, 2015). "Before challenge infection with RSV, we also examined the effector CD4 and CD8 T cell responses upon in vitro stimulation of various RSV specific peptides (F51-66, G183-195 as CD4 T cell epitope, F85-93 and M282-90 as CD8 T cell epitope) to better understand the effector T cell responses." (PMID 26468884, 2015). "In contrast, reduced frequencies of CD4+CCR5+ T cells were readily observed during the same period in the spleen and in the bone marrow if HIV-infected or non-infected HuMice were compared at the end of the experiment 37 days after infection." (PMID 26407077, 2015). "Subcutaneous infection of mice with F. pedrosoi spores induced the activation, expansion, and differentiation of Ag‐specific CD4+ T cells but TLR costimulation did not further augment these T‐cell responses." (PMID 26140582, 2015). "Patients with advanced HIV disease at the time of starting ART, defined by low CD4 count and World Health Organization (WHO) clinical stage 3 or 4 of infection, are less likely to respond to treatment and have a higher mortality rate compared with those who start treatment earlier." (PMID 25604750, 2015). "Despite expressing moderately high levels of CD69, untreated CD4+ T cells isolated from tonsillar tissue did not give rise to significantly higher levels of productive infection (0.68%) compared to CD4+ T cells from peripheral blood." (PMID 26067822, 2015). "While no change was observed in the frequency of CD4+TNF-alpha+ T cells after 72 hours of infection with either T. cruzi strain, our data showed an increase in the frequency of CD8+TNF-alpha+ T lymphocytes." (PMID 26147698, 2015). "Intracellular staining of CD4+ T lymphocytes revealed that mice reconstituted with CD4+Foxp3- T cells and CD4+Foxp3- T cells + Treg showed augmented production of IFN-γ, IL-17 and IL-4, at weeks 2 and 6 post-infection, when compared with mice receiving Treg cells only." (PMID 26512987, 2015). "However, CD4+ T cell counts in TPs decreased slowly at a rate of 33 cells/μL/year, before patients (TPs) received ART after 3 years of infection." (PMID 26286082, 2015). "However, the possibility that one virus would directly exclude infection by the other, would be unexpected given that the number of HIV infected CD4+ T cells in the periphery is considered to be relatively low (i.e., ~1.4% of the total subpopulation)." (PMID 26390290, 2015). "Later in infection, CD8+ and to a lesser extent CD4+ T cells become the main IFNγ producers." (PMID 26070118, 2015). "During primary infection with VACV, deletion of N1 or a I6E mutation resulted in enhanced CD8+ T-cell (but not CD4+ or NK) cytotoxicity, increased numbers of CD8+ (but not CD4+) TCM and TEM cells, and better protection against challenge with VACV." (PMID 25382035, 2015). "All groups showed an increased frequency of CD4+ TEM cells compared to G2 (p<0.01), and this trend was especially notable for G5, which was significantly increased compared to G3 at both 5 and 10 weeks post-infection." (PMID 26509812, 2015). "Moreover, the amount of IFN-γ producing CD4+ T cells increased after PCV2 vaccination and/ or infection." (PMID 25888899, 2015). "However, the course of infection clearly differed in CD8+-T-cell-depleted and CD4+-T-cell-depleted mice." (PMID 25760084, 2015).
infection (continued). "GCA induced activation of FXR at post-booster stages in vaccinated animals may reduce macrophage and neutrophil influx to the site of infection and increase the levels of INF-γ producing CD4+ and CD8+ T-cells, promoting an adaptive immune response." (PMID 25828073, 2015). "HIV-1 activation did not take place in PMA stimulated CD4+ T lymphocytes treated with AZT before infection, demonstrating that the results from FACS analysis were not biased by carryover from the viral input." (PMID 26502902, 2015). "Analysis of cells in the posterior cervical lymph nodes proximal to the infection site showed similar results for the total cell numbers, CD8+ T cells and other cell subsets including CD4+ T cells, B cells, NK cells, macrophages and neutrophils (not shown)." (PMID 25382035, 2015). "JRCSFNefdd infection did not activate CD8+ T cells or reduce the level of CD4+ T cells in blood but did result in a small Nef-independent decrease in CD4+ T cells in organs." (PMID 26169178, 2015). "Iron supplementation did not change the percentage of CD4+ T cells, but the percentage decreased during infection in the control mice." (PMID 25768944, 2015). "Additionally, elderly individuals exhibit a shift from a naïve to a memory repertoire in CD4+ T cells, CD8+ T cells, and B cells, which decreases the number of cells capable of recognizing new antigens encountered during primary infections." (PMID 26204259, 2015). "The absence of CD4+ T cells in the recipient animals 12 days after infection was confirmed by flow cytometry, strongly suggesting that the antiviral effect of the adoptively transferred cell population rests on γδ T cells." (PMID 25658831, 2015). "The simulation shows that if the treatment effectiveness is very high, then CD4+ count can rebound to its pre-infection level no matter when HAART is initiated." (PMID 26709961, 2015). "The accumulation of TFH (CD4+ PD1+ CXCR5+) and GC B (CD19+ Fas+ GL7+) cells was decreased in old mice relative to adult mice at days 4 and 6, although nearly equivalent levels of TFH and GC B cells were present at 8 days post infection." (PMID 26204259, 2015). "Infected cells that expressed GFP had wild-type levels of surface CD4, suggesting that infection alone with an HIV Env-pseudotyped virus did not lead to CD4 internalization." (PMID 26537682, 2015). "We propose a mechanism to explain the infection of Vδ2 cells despite the absence of CD4 expression in their surface." (PMID 26473478, 2015). "Considering that CD4+ T cells are required for the increased IEC proliferative response during infection, we tested if Rag1-/- mice were impaired in RELM-β production, but instead found it was strongly expressed in their colons during infection." (PMID 26285214, 2015). "Analysis of non-specific CD4+ T cell polyfunctionality revealed a higher quantity in mono-functional cells from HIV mono-infection to HIV/LTBI to HIV+/TB." (PMID 25781898, 2015). "In contrast to IN pigs, no further increase of single or double cytokine-producing CD4+ T cells was observed after PCV2 infection." (PMID 25888899, 2015). "Thus, our data identify IL-27 signaling as a novel pathway to prevent early mortality via inhibiting hyperactivation of CD4+ Th1 cells and their excessive secretion of IFN-γ during infection with African trypanosomes." (PMID 26222157, 2015). "Therefore, we measured the expression of IL4Rα (receptor) on CD4+ T cells by flow cytometry and IL13 (ligand) expression in the lung by real-time PCR during primary infection." (PMID 26231396, 2015). "CD4+ T cells are essential for helping antibody production by B cells, but detailed data on the functionalities of TBEV-specific CD4+ T cells in response to infection or vaccination are lacking." (PMID 26465323, 2015).